INS (insulin)
Diseases named in the same sentence as INS in open-access papers (continued):
Sharing a sentence is not in itself a finding about the gene and the disease.
type 2 diabetes (continued). "Increased PHOSPHO1-imputed expression was associated with higher insulin levels; previous literature reports that decreased methylation status in the body of these gene increases risk of developing type 2 diabetes." (PMID 30624610, 2019). "Because the liver is the major site of insulin clearance, dysfunctional insulin capture for degradation is a risk factor for type 2 diabetes and obesity." (PMID 30621263, 2019). "This indicates that β-cell functional impairment rather than simply β-cell loss largely contributes to the insufficient insulin secretion and glycemic control in type 2 diabetes." (PMID 30450940, 2019). "The causes of type 2 diabetes include both genetic, lifestyle and environmental elements that affect β-cell function and insulin sensitivity." (PMID 31890678, 2019). "This association between methylation levels and insulin sensitivity does not overlap with those variants at the KCNQ1 locus previously linked to type 2 diabetes risk via insulin secretion impairment." (PMID 30641161, 2019). "This particular pattern was nominally associated with increased levels of insulin, a finding consistent with current literature, suggesting meat consumption to be associated with hyperinsulinaemia and type 2 diabetes." (PMID 31847144, 2019). "The insulin resistance of peripheral tissues as well as the impairment of glucose-induced insulin secretion from pancreatic β cells causes type 2 diabetes." (PMID 31455007, 2019). "Ginsenoside Rb1, one of the main PPD-type ginsenosides, was found to reduce symptoms of decreased insulin sensitivity and elevated blood glucose caused by the high-fat diet induction of type 2 diabetic mice." (PMID 31835292, 2019). "Type 2 diabetes is associated with chronic low-grade inflammation, which engenders both metabolic and microvascular insulin resistance through endocrine, autocrine and paracrine actions of multiple pro-inflammatory factors." (PMID 30699907, 2019). "Type 2 diabetes is typically associated with normal insulin production, but lower insulin sensitivity of cells, which in consequence leads to elevated glucose levels in the blood." (PMID 31757001, 2019). "When people become more obese, they reach an abnormal insulin resistant state, causing impaired glucose tolerance, which ultimately leads to the onset of type 2-diabetes." (PMID 31249794, 2019). "This study aimed to investigate the safety of insulin degludec (degludec) in relation to age and risk of hypoglycaemia post hoc in individuals with type 2 diabetes (T2D) (SWITCH 2 trial)." (PMID 30891886, 2019). "The amount of fat can influence insulin sensitivity and the risk of developing type 2 diabetes only with intakes greater than 35–40% of total energy intake." (PMID 31450565, 2019). "Residual endogenous insulin secretion is associated with both DR prevalence and its severity in Latinos with familial type II diabetes." (PMID 31331327, 2019). "Insulin administration was found to trigger type 1 diabetes in six Japanese type 2 diabetes patients with type 1 diabetes high‐risk human leukocyte antigen class II and the class I allele of the insulin gene variable number tandem repeat genotype." (PMID 30970177, 2019). "Overall, pancreatic atrophy was associated with the loss of insulin secretory capacity in patients with type 2 diabetes." (PMID 31467928, 2019). "GC variants have formerly been associated with type 2 diabetes in seven Polynesian populations, and insulin regulation and glucose in a Hispanic-American/Anglo population of Southern Colorado and Dogrib Indians of Canada." (PMID 31007727, 2019). "The metabolite ratio of valine to PC ae C32:2 (Val/PC ae C32:2) was previously reported to be associated with an increased risk of type 2 diabetes and measures of insulin secretion and resistance." (PMID 30634984, 2019).
type 2 diabetes (continued). "First, we used large-scale genome-wide association studies (GWAS) to identify genetic variants associated with obesity measures, blood pressure, lipids, type 2 diabetes, insulin, and glucose." (PMID 30605491, 2019). "In particular, the branched-chain amino acids (BCAAs) leucine, isoleucine and valine are essential amino acids synthesized by gut bacteria and are associated with insulin resistance and increased risk of type 2 diabetes." (PMID 31213483, 2019). "This mirrors the effect of fasting and very low calorie diets, which improve insulin sensitivity and reverse type 2 diabetes, but also can cause a form of glucose intolerance known as benevolent pseudo-diabetes." (PMID 31406105, 2019). "Type 2 diabetes is characterized by dysregulation of carbohydrate, lipid, and protein metabolism caused by impaired insulin signaling resulting from reduced insulin secretion, insulin resistance, or the combination of both." (PMID 31798464, 2019). "Most patients with SGLT2 inhibitor-associated euDKA have type 1 diabetes or latent autoimmune diabetes in adults (LADA) or have long-standing insulin deficient type 2 diabetes and develop DKA in the presence of stress and illness." (PMID 31198610, 2019). "The inability of insulin to suppress hepatic glucose production is the primary cause of type 2 diabetes." (PMID 31075962, 2019). "Type 2 diabetes is caused by the combination of a decrease in the effect of insulin acting in the body, associated with the inability of the β-pancreatic cells to produce adequate amounts of insulin." (PMID 31089412, 2019). "Type 2 Diabetes (T2D), a chronic disease caused by a reduction in the effectiveness of insulin’s control over blood sugar, is increasing in the United States and globally." (PMID 31810250, 2019). "This is of particular relevance because decreased insulin sensitivity is thought to be the underlying linkage between obesity, type 2 diabetes and CV disease." (PMID 31620011, 2019). "GPR40 agonists have the potential to be key drugs for increasing insulin levels with minimal risk of iatrogenic hypoglycemia in patients with type 2 diabetes." (PMID 31498851, 2019). "IR, which is caused by deficits at several levels of the insulin signaling pathway, is the major feature of type 2 diabetes and also commonly associated with the development of hypertension and atherosclerosis." (PMID 30993115, 2019). "IR, as the most common pathological condition in which cells in the body become resistant to the normal functions of insulin, is associated with type 2 diabetes, hypertension, atherosclerosis and NAFLD etc.." (PMID 31551937, 2019). "It has also been shown that dietary intake of α-linolenic acid is associated with beneficial effects on cardiometabolic risk factors and insulin sensitivity, thereby reducing the progression to cardiovascular disease and type 2 diabetes." (PMID 30871233, 2019). "The incidence of type II diabetes with hyperglycemia is increasing worldwide; it is a heterogeneous disease with progressive decline in insulin sensitivity causing pancreatic β-cell dysfunction." (PMID 31170991, 2019). "Hypoglycaemia during exercise, or for up to 12 h after exercise, is the main risk for individuals with type 2 diabetes taking insulin and/or sulfonylurea medication." (PMID 31161377, 2019). "Low osteocalcin serum levels in human is associated with an increased risk of diabetes type 2 as osteocalcin increases insulin sensitivity in human and animals, and insulin sensitivity is improved after cold stress." (PMID 31827442, 2019). "Decreased insulin sensitivity is associated with a wide range of common disorders including type 2 diabetes, obesity, hypertension and cardiovascular disease." (PMID 30641161, 2019). "Type 2 diabetes is a metabolic disease that is associated with obesity, reduced insulin-stimulated glucose uptake by skeletal muscle and adipose tissue, and impaired β cell function." (PMID 31075957, 2019).
type 2 diabetes (continued). "Higher fasting insulin levels are associated with numerous adverse risk factors in young adults, increasing the risk of atherosclerosis and subsequent type 2 diabetes." (PMID 30138332, 2018). "Regarding non-severe and any hypoglycemia, patients with higher frequency of blood glucose monitoring, longer duration of insulin therapy, and type 2 diabetes had higher risk." (PMID 30479669, 2018). "It has been proven that higher insulin levels in early childhood are associated with increased risk of type 2 diabetes during adult life exposure to air pollutants." (PMID 30463387, 2018). "Supportive of a potential fear modulating role for glucagon, type II diabetes patients, which have both elevated insulin and glucagon levels, have an increased risk to develop anxiety disorders (OR = 1.25 (CI 1.10–1.39))." (PMID 30210279, 2018). "Decreased adiponectin levels were demonstrated to be associated with decreased insulin sensitivity and to precede the onset of type 2 diabetes." (PMID 30034345, 2018). "Impaired insulin signaling in skeletal muscle disturbs glucose transporter 4 (GLUT4) translocation associated with the onset of type 2 diabetes (T2D)." (PMID 30410865, 2018). "Prior reports confirmed that MTNR1B rs10830963 is a true causal gene variant in type 2 diabetes development which impaired the early-phase insulin response and also increased the odds of GDM development." (PMID 30477160, 2018). "IAH also occurs in type 2 diabetes, affecting up to 10% of patients with insulin-treated type 2 diabetes and markedly increasing risk of severe hypoglycaemia." (PMID 29417183, 2018). "Insulin deficiency is caused by a reduction in the number of insulin-producing β-cells in both type 1 and type 2 diabetes." (PMID 30510621, 2018). "ReferencesIntensive blood-glucose control with sulphonylurea or insulin compared with conventional treatment and risk of complications in patients with type 2 diabetes (UKPDS 33)." (PMID 29527102, 2018). "In humans and mice mutations in insulin pathway genes cause severe insulin resistance syndromes and type 2 diabetes." (PMID 30271425, 2018). "The resulting hyperinsulinaemia desensitises insulin-sensitive tissues, which predisposes individuals to type II diabetes." (PMID 29755739, 2018). "Age (OR of 1.79, 95% CI 1.47–2.18) and use of insulin (OR of 2.11, 95% CI 1.43–3.11) were associated with increased risk of cataract in patients with type 2 diabetes." (PMID 29386666, 2018). "Type 2 diabetes has the characteristics of chronic hyperglycemia and dyslipidemia caused by insulin resistance of the peripheral tissues and impaired insulin secretion from the pancreas, which is difficult to cure." (PMID 29599810, 2018). "Type 2 diabetes is strongly associated with decreases in insulin-stimulated glycogen synthase activity and glycogen synthesis and with increased GSK3 protein levels." (PMID 29681858, 2018). "Intensive blood-glucose control with sulphonylureas or insulin compared with conventional treatment and risk of complications in patients with type 2 diabetes (UKPDS 33)." (PMID 29527102, 2018). "Type 2 diabetes is a complex disorder; its underlying mechanism is mostly related to defects in insulin secretion and action." (PMID 30013597, 2018). "MTNR1B, a melatonin receptor gene, is a common variant associated with an increased risk of future type 2 diabetes and impaired early insulin secretion." (PMID 29777116, 2018). "Fat accumulation outside adipose tissue, i.e. ectopic fat in liver and muscle, is linked to decreased insulin sensitivity and type 2 diabetes." (PMID 29696296, 2018). "This has been done in development of the PEGylated version of the analogue insulin lispro which has been reported to be associated with a half-life of 2–3 days in people with type 2 diabetes." (PMID 30116732, 2018). "Impaired insulin secretion due to the dysfunction/loss of pancreatic β cells significantly contributes to the development of both type 1 and type 2 diabetes." (PMID 29518025, 2018).
type 2 diabetes (continued). "In humans and mice insulin pathway impairment, due to mutations, cause severe insulin resistance syndromes and type 2 diabetes (reviewed in33)." (PMID 30061626, 2018). "Our present study was undertaken to estimate serum Lp(a) levels in Libyan patients with type 2 diabetes, and find out its association with glycemic control, lipid profile, and serum insulin." (PMID 30254819, 2018). "Type 2 diabetes risk and levels of glucose, insulin, and HbA1c are heritable traits correlated with risk of other diseases and mortality." (PMID 29621232, 2018). "Deterioration in insulin signaling or insulin resistance in skeletal muscle cells is one of hallmark features of type II diabetes." (PMID 29872751, 2018). "Type 2 diabetes is the most common complication associated with obesity and is characterised by reduced insulin sensitivity and increased visceral fat." (PMID 29914108, 2018). "Our results suggest that an rCP sample can identify patients with insulin-treated type 2 diabetes who have a markedly increased risk of hypoglycaemia." (PMID 28983693, 2018). "Insulin replacement therapy is mostly used by patients with type 2 diabetes who become insulin deficient and have failed other therapeutic options." (PMID 29682315, 2018). "Type 2 diabetes is a metabolic disorder characterised by insulin resistance in target tissues and deficiency of insulin secretion in the pancreas." (PMID 29349498, 2018). "Type 2 diabetes is caused by a combination of resistance to insulin action and an inadequate compensatory insulin secretory response." (PMID 30382190, 2018). "In this study we have shown that the Val_PC ae C32:2 metabolite ratio is associated with an increased risk of type 2 diabetes and measures of insulin secretion and resistance." (PMID 28936587, 2018). "The accumulation of non-native disulfide-bonded insulin following glucose stimulation can lead to loss of insulin secretion, oxidative stress, and apoptosis, resembling pathologies seen in type II diabetes." (PMID 29153511, 2018). "Type 2 diabetes is an age-and-obesity associated disease driven by impairments in glucose homeostasis that ultimately result in defective insulin secretion from pancreatic β-cells." (PMID 30546031, 2018). "The early stage of diabetes mellitus type 2 is associated with postprandial hyperglycemia due to impaired after meal acute insulin secretion." (PMID 30003087, 2018). "We discovered for the first time that lysoPC(19:1) and PC(17:0/18:2) were associated with higher insulin sensitivity and inversely associated with type 2 diabetes." (PMID 29349498, 2018). "Until now, there has not been a thorough documentation and characterisation of the progression of retinal pathology in type 2 diabetes associated with chronic obesity and insulin insensitivity." (PMID 30094465, 2018). "Linked with increasing rates of obesity, the more prevalent Type 2 diabetes is caused by cellular resistance to insulin and the failure of β-cells to compensate." (PMID 30425651, 2018). "The liver plays a pivotal role in the regulation of human glucose metabolism, and defects in hepatic insulin signaling predispose to hyperglycemia and type 2 diabetes (T2D)." (PMID 29941634, 2018). "The loss of early-phase insulin secretion is a symptom of type 2 diabetes and glucose intolerance and is associated with hyperglycemia." (PMID 29617350, 2018). "The analysis of metabolite profiles and ratios in response to different insulin secretagogues are thus relevant for further elucidating the underlying biology of the development of type 2 diabetes." (PMID 28936587, 2018). "Insulin resistance occurs when the insulin signaling pathway is impaired, and it is termed one of the most prevalent metabolic abnormalities, which causes obesity and type 2 diabetes (T2D)." (PMID 29522441, 2018). "Type 2 diabetes is characterized by both a loss of insulin sensitivity and, ultimately, a relative loss of insulin secretion from the pancreatic β-cell." (PMID 29371604, 2018).
type 2 diabetes (continued). "Intensive blood glucose control with sulphonylureas or insulin compared with conventional treatment and risk of complications in type 2 diabetes (UKPDS33)." (PMID 29527102, 2018). "Specifically, a gain-of-function variant of LPL was associated with higher insulin sensitivity, lower fasting glucose and a lower risk of type 2 diabetes." (PMID 29502266, 2018). "In the Prospective Study of Pravastatin in the Elderly at Risk (PROSPER) study, HOMA-IR was more strongly associated with incident type 2 diabetes than fasting insulin, which corresponds to the observations in our study." (PMID 29018885, 2018). "In recent EWASs, around 60% of the methylation changes associated with age in pancreatic islets also occur in blood, including FHL2, KLF14, FAM123C and GNPNAT1, all genes known to be associated with type 2 diabetes or insulin secretion." (PMID 29164275, 2018). "In a long term prospective study of type 2 diabetes, metformin was associated with reduced cardiovascular and all-cause mortality compared to sulphonylureas and insulin despite similar glycaemic control (UKPDS)." (PMID 29973490, 2018). "High glucose levels are known to be closely associated with β-cell dysfunction in type 2 diabetes, and abnormal glucose-stimulated insulin secretion (GSIS) can explain the mechanism." (PMID 30134927, 2018). "Glucagon-like peptide-1 receptor (GLP-1R) activation promotes insulin secretion from pancreatic beta cells, causes weight loss, and is an important pharmacological target in type 2 diabetes (T2D)." (PMID 29686402, 2018). "It went further to assess the effects of the aqueous-methanol extracts on intracellular oxidative stress and the expression level of genes associated with type 2 diabetes in insulin-resistant C2C12 skeletal muscle cells." (PMID 30126082, 2018). "Type 2 diabetes is a metabolic syndrome caused by an unbalanced production and/or action of the hormone insulin." (PMID 30018269, 2018). "We find that p.E40K in ANGPTL4 is associated with lower fasting glucose and greater insulin sensitivity in humans, as well as reduced risk of type 2 diabetes." (PMID 29899519, 2018). "Another M1 hub protein, SORBS1, which functions in insulin signaling, has also been associated with obesity and type 2 diabetes." (PMID 29490708, 2018). "In most studies, diet-induced weight loss in people with type 2 diabetes causes an increase in hepatic insulin sensitivity, but some authors report it unchanged." (PMID 29696296, 2018). "Of 55 individuals who were f-GADA-positive but t-GADA-negative, i.e. with antibody binding restricted to the N-terminus of GAD65, the phenotype was similar to type 2 diabetes with low risk of progression to insulin treatment." (PMID 29619531, 2018). "While many experimental studies have sought to elucidate mechanisms underlying the enhanced propensity for arrhythmia in insulin-dependent models of type 1 diabetes, those driving arrhythmogenesis in type 2 diabetes are far less investigated." (PMID 30425651, 2018). "In conclusion, we found that loss-of-function variants in ANGPTL4 were associated with increased insulin sensitivity and reduced risk of type 2 diabetes, mirroring the beneficial effects on glucose homeostasis of deletion of Angptl4 in mice." (PMID 29899519, 2018). "In type 2 diabetes, the glucose control network is largely preserved, but insulin secretion is deficient relative to hepatic and peripheral insulin resistance." (PMID 32232090, 2018). "Type 2 diabetes is caused by an insufficient insulin level or hyposensitivity of the cells in the body to insulin, whereas gestational diabetes occurs in females during pregnancy and requires careful management to avoid complications in the child." (PMID 30384450, 2018). "Type II diabetes mellitus, which is different from type I diabetes mellitus, involves basal insulin secretion and basal insulin sensitivity abnormalities caused by the inheritance of multiple recessive genes." (PMID 30131712, 2018).